TIMP1 (TIMP metallopeptidase inhibitor 1)
Diseases named in the same sentence as TIMP1 in open-access papers (continued):
Sharing a sentence is not in itself a finding about the gene and the disease.
Hepatic steatosis (11 papers, 2015 to 2025). Steatosis is a term used to denote lipid accumulation within hepatocytes. "We found TIMP-1 deficiency to be associated with altered hepatic metabolism, thereby contributing to improved hepatic function, decreased hepatic inflammation and decreased hepatic steatosis." (PMID 26168159, 2015). "The results of the present study showed that in comparison with the fatty liver groups, the combination therapy group (NAFLD+LGG+HIIT) caused a significant decrease in TIMP-1 mRNA compared to the NAFLD group." (PMID 36110559, 2022). "Since hepatic overexpression of constitutively active Akt is known to induce hepatic steatosis, TIMP-1 may act through binding to CD63 and phosphorylation of Akt, thereby promoting hepatic steatosis." (PMID 26168159, 2015). "Collectively, our results indicate that TIMP-1 contributes to the development of diet-induced hepatic steatosis and glucose intolerance and may be a potential therapeutic target." (PMID 26168159, 2015). "TNF knockout reduced the progression of hepatic steatosis and fibrosis by downregulation of MCP-1, TGF-1β, Col1a1, and TIMP-1 in transgenic mice." (PMID 31001563, 2019). "When hepatic steatosis develops, HSCs are activated and express several fibrosis markers in vitro, such as TGF-β, TIMP-1, TIMP-2, and matrix-metallo-proteinase-242." (PMID 28623272, 2017). "Here we investigated how the presence or absence of TIMP-1 affected the development of diet-induced glucose intolerance and hepatic steatosis using the Timp1 null mice." (PMID 26168159, 2015). "TIMP-1 deficient mice were protected from HFD- and IFSD-induced development of hepatic steatosis and glucose intolerance, but TIMP-1 deficiency did not change peripheral insulin sensitivity or insulin secretion." (PMID 26168159, 2015).
lymphoma (11 papers, 2005 to 2023). A malignant (clonal) proliferation of B- lymphocytes or T- lymphocytes which involves the lymph nodes, bone marrow and/or extranodal sites. "No study has previously reported the increased expression of Ig heavy chain V region GOM associated with canine lymphoma in the same way as with TIMP-1, APOH, and CD44." (PMID 35765478, 2022). "In hematological malignancies, TIMP-1 promotes differentiation of lymphoma cells, whereas increased TIMP-1 serum levels are associated with advanced myeloma." (PMID 27903985, 2017). "The gelatinase MMP-9 and its inhibitor TIMP-1 mediate breakdown of the extracellular matrix during inflammatory and other responses, and one or both have been linked to lymphoma at the time of diagnosis." (PMID 24922518, 2014). "An initial hint at an important role for TIMP-1 in hepatic PMN formation has been the finding that elevated systemic levels of TIMP-1 promote the scattered infiltration of T lymphoma cells throughout the parenchyma of the liver." (PMID 29903049, 2018). "For instance, drug treated endothelial cells release IL-6 and Timp-1, which promote the induction of Bcl-xl in adjacent lymphoma cells." (PMID 25185441, 2014). "These molecules are associated with a more aggressive clinical behaviour in human lymphoma, and they appear to exert their influence through two different mechanisms: MMP-9 causes ECM degradation, whereas TIMP-1 shows an anti-apoptotic action." (PMID 23641796, 2013). "The first reported serum proteins in canine lymphoma were ACTB, Ig heavy chain V region GOM, TIMP-1, APOH, CD44, APOC1, and β2M." (PMID 35765478, 2022). "Potential novel candidate biomarkers in canine lymphoma were ACTB, β2M, TIMP-1, CD44 antigen, Ig heavy chain V region GOM, APOC1, and APOH." (PMID 35765478, 2022). "ACTB, aaaaaaaa2M, APOH, TIMP-1, CD44 antigen, Ig heavy chain V region GOM, and APOC1 are novel candidate proteins and might serve as a lymphoma biomarker in dogs." (PMID 35765478, 2022). "Six candidate increased proteins in canine lymphomas were beta-actin cytoplasmic 1 (ACTB, p=0.04), haptoglobin (p=0.002), beta-2 microglobulin (aaaaaaaa2M, p=0.007), beta-2 glycoprotein 1 (APOH, p=0.03), metalloproteinase inhibitor 1 (TIMP-1, p=0.03), and CD44 antigen (p=0.02)." (PMID 35765478, 2022). "Differently higher serum proteins in canine lymphoma were observed in beta-actin cytoplasmic 1 (ACTB, p=0.04), Hp (p=0.002), beta-2 microglobulin (β2M, p=0.007), beta-2 glycoprotein 1 (APOH, p=0.03), metalloproteinase inhibitor 1 (TIMP-1, p=0.03), and CD44 antigen (p=0.02)." (PMID 35765478, 2022).
renal cell carcinoma (11 papers, 2006 to 2024). "In conclusion, the present results suggested that TIMP1 indicated poor prognosis of renal cell carcinoma and could serve as a potential diagnostic and prognostic biomarker for RCC." (PMID 35281807, 2022). "In human renal cell carcinoma cell lines, Tiam1 inhibits invasion through Rac-induced upregulation of tissue inhibitor of metalloproteinases-1 (TIMP-1) and TIMP-2." (PMID 24069171, 2013). "TIMP1 is highly expressed in a plethora of tumours including colon, pancreas, breast, gastric, esophageal, diffuse large B‐cell lymphoma, and renal cell carcinoma, in addition to non‐neoplastic tissues like the adipose tissue." (PMID 37759102, 2023). "TIMP1, a key tissue inhibitor of metalloproteinase that regulates most matrix metalloproteinases, was usually found to be increased in renal cell carcinoma (RCC) and could affect the efficiency of radiotherapy." (PMID 36035192, 2022). "The expression of TIMP1 in renal cell carcinoma regulates the IL6-JAK-STAT3 pathway." (PMID 32420905, 2020). "Mean MMP-2, MMP-9, MT1-MMP, TIMP-1, and TIMP-2 mRNA expression in the renal cell carcinomas was significantly higher than in the normal renal tissue." (PMID 23281640, 2013). "Mean MMP-2, MMP-9, MT1-MMP, TIMP-1, and TIMP-2 mRNA expression in the renal cell carcinomas was significantly higher than in the normal renal tissue (P <0.05)." (PMID 23281640, 2013). "In the present study, mean MMP-2, MMP-9, MT1-MMP, TIMP-1, and TIMP-2 mRNA expression in the renal cell carcinomas was significantly higher than in the normal renal tissue (P <0.05)." (PMID 23281640, 2013). "In summary, mean MMP-2, MMP-9, MT1-MMP, TIMP-1, and TIMP-2 mRNA expression in the renal cell carcinomas was significantly higher than in the normal renal tissue (P <0.05)." (PMID 23281640, 2013). "In this study, we examined the expression of MMP-2, MMP-9, membrane-type 1 (MT1)-MMP, TIMP-1, and TIMP-2 in renal tissue samples of renal cell cancer and examined the correlation between their expression and clinicopathological parameters." (PMID 23281640, 2013). "Adiponectin, via AdipoR1, inhibits mTOR through AMPK activation in renal cell carcinoma (RCC), suppresses vascular endothelial growth factor (VEGF), MMP-2 and MMP-9 and increases TIMP-1 and TIMP-2 secretion, resulting in decreased growth, dissemination and angiogenesis of RCC." (PMID 37686525, 2023). "Furthermore, TIMP-1 and TIMP-2 expression by immunohistochemistry has been found to be significantly correlated with poor prognosis in renal cell carcinoma." (PMID 23281640, 2013). "In the present study, we examined the expression of MMP-2, MMP-9, MT1-MMP, TIMP-1, and TIMP-2 mRNA in human renal cell carcinoma tissues by a reverse transcriptase-polymerase chain reaction (RT-PCR) assay and examined the correlation between their expression and clinicopathological parameters." (PMID 23281640, 2013). "In terms of pathologic grade of renal cell carcinoma, the differences in MMP-2, MMP-9, MT1-MMP, TIMP-1, and TIMP-2 mRNA expression levels were not significant." (PMID 23281640, 2013).
tendinopathy (11 papers, 2015 to 2025). "Further research is necessary to fully understand the role of HIF-1 and TIMP-1 in tendinopathy and to develop effective treatments for this debilitating condition." (PMID 38247510, 2024). "Evidence on TIMPs showed that TIMP-1 expression is briefly augmented (compensation) after acute tendon tear and reduced in tendinopathy, whereas TIMP-2, TIMP-3, and TIMP-4 are downregulated in both tendinopathy and tears." (PMID 36830637, 2023). "Both MMP inhibitors and upregulation of TIMP1 (with controlled exercise) have been suggested as having potential in the treatment of tendon disorders." (PMID 29023489, 2017). "One possible mechanism by which HIF-1 may contribute to tendinopathy is the regulation of MMP3 by its activator TIMP-1." (PMID 38247510, 2024). "Previous research has indicated that TIMP-1 hinders excessive matrix degradation by impeding MMP activity, especially that of MMP-9, as MMP-2 and MMP-9 are upregulated in tendinopathies." (PMID 38247510, 2024). "Abnormal extracellular matrix (ECM) remodeling was a key characteristic and pathological progress in tendinopathy, and increased COL I, COL III, MMP3 and MMP9 expression as well as decreased COL III/COL I rate and TIMP-1 content were detected in the tendinopathy mice." (PMID 36604715, 2023). "We did not observe any changes in other matrix proteins or tissue inhibitors of metalloproteinases (TIMP1 and TIMP2) therefore, in the context of tendinopathy, MMP3 may regulate inflammation in addition to influencing matrix remodelling." (PMID 30728384, 2019).
ulcerative colitis (11 papers, 2008 to 2025). An inflammatory bowel disease involving the mucosal surface of the large intestine and rectum. "The study further identified that TIMP1 facilitates the progression of ulcerative colitis via a dual mechanism involving T cell depletion and macrophage activation." (PMID 40433374, 2025). "In this study, we determined MMP-1 and TIMP-1 expression levels in ulcerative colitis patients compared with normal controls." (PMID 19911067, 2009). "This study aims to evaluate the relationship between colonic mucosal and plasma levels of MMP-1 and TIMP-1 with each other and with the severity of ulcerative colitis (UC)." (PMID 19911067, 2009). "Multiple studies, utilizing bioinformatics, machine learning, clinical database analysis, and experimental validation, have found that TIMP1 is involved in regulating the ferroptosis process in ulcerative colitis and can serve as a biological indicator for its diagnosis and prediction." (PMID 40687427, 2025). "Additionally, we also investigated the expression of TIMP1 mRNA in the platelets from 22 patients with ulcerative colitis and 23 patients with Crohn’s disease." (PMID 31639773, 2019). "In addition, MMP-1 and TIMP-1 expression increased with the severity of ulcerative colitis." (PMID 19911067, 2009). "The aim of our study was to evaluate the expression of MMP-2, MMP-7, MMP-9, TIMP-1, and TIMP-2 in ulcerative colitis and Crohn's disease." (PMID 27034654, 2016). "TIMP-1, TIMP-2 and TIMP-4 serum levels were determined in 53 patients with ulcerative colitis (UC), 52 patients with Crohn's disease (CD) and 50 HC, by means of commercially available enzyme-linked immunosorbent assays." (PMID 19036126, 2008). "Unlike in ulcerative colitis, where TIMP1 upregulation contributes to matrix remodeling but not directly to malignancy, our functional assays confirm that TIMP1 knockdown selectively impairs CRC cell proliferation and ferroptosis resistance." (PMID 40687427, 2025).
cardiac hypertrophy (10 papers, 2015 to 2022). "More importantly, our results suggested that rapamycin alleviated the dysregulation of MMP-9/TIMP-1 balance while improving Testosterone-induced OVX SHR cardiac hypertrophy." (PMID 34874016, 2022). "In the present study, the high expression of MMP-9 and the low expression of TIMP-1 displayed imbalance in the Testosterone-induced cardiac hypertrophy of OVX SHR." (PMID 34874016, 2022). "The DEGs associated with cardiac hypertrophy were screened via bioinformatics analysis, and eight hub genes were identified, including Akt1, Lox, Timp1, Col1al, Spp1, Ccnd1, Mmp3, and Egfr, which might be a new target for the identification of cardiac hypertrophy." (PMID 36046382, 2022). "Clinical studies have shown that myocardial TIMP-1 and TIMP-2 mRNA expression is increased in patients with aortic stenosis, and myocardial MMP-1 and TIMP-1 protein expression is increased in patients with myocardial hypertrophy." (PMID 25861361, 2015). "Importantly, although socially stressed rats did not demonstrate ventricular hypertrophy, witness stressed rats exhibited robust increases in Timp-1 over that of controls and intruder rats." (PMID 28241050, 2017).
chronic hepatitis C (10 papers, 2006 to 2026). "Timp1 and other extracellular matrix remodeling genes are implicated in the transition from mild to moderate fibrosis in patients with chronic hepatitis C." (PMID 17118137, 2006). "(2013) for chronic hepatitis C patients included variables such as hyaluronic acid, TGF-β1, α2-macroglobulin, Matrix Metalloproteinase (MMP)-2, apolipoprotein-A1, urea, MMP-1, alpha-fetoprotein, haptoglobin, red blood cell count, hemoglobin, and TIMP-1." (PMID 41551471, 2026).
Crohn disease (10 papers, 2008 to 2025). A gastrointestinal disorder characterized by chronic inflammation involving all layers of the intestinal wall, noncaseating granulomas affecting the intestinal wall and regional lymph nodes, and transmural fibrosis. "A previous study showed that humans carrying the T allele in the 372 T/C genetic polymorphism of TIMP-1 had increased susceptibility to Crohn's disease and presented lower levels of TIMP-1 in surgically resected macroscopically inflamed tissue." (PMID 23706069, 2013). "An increased level of TIMP-1 has been shown in fibrotic lesions in Crohn’s disease and a murine colitis model." (PMID 31189971, 2019). "An increased level of TIMP-1 protein has been reported in inflammatory and fibrotic lesions in Crohn’s disease and a murine model of chronic inflammation-induced intestinal fibrosis." (PMID 31189971, 2019). "Current research has implicated a close correlation between key ferroptosis-related genes such as TIMP1, CAV1, CD44, HIF1A, and IFNG, and immune infiltration in Crohn’s disease." (PMID 40687427, 2025).
diabetic nephropathy (10 papers, 2015 to 2025). "A variety of studies using human renal samples underlying the correlation between Nampt/Sirt6 /TIMP-1 and diabetic nephropathy have been reported, which includes the important roles of these molecules mainly in the middle to late stages of DN." (PMID 38587753, 2024). "This is the first study that assessed associations of MMP-9 and TIMP-1 with long-term microvascular complications in type 1 diabetes, primary diabetic neuropathy, and diabetic nephropathy." (PMID 33775157, 2021). "Previous studies have shown that TIMP1 is overexpressed in the kidney tissue of diabetic nephropathy rats." (PMID 30547763, 2018). "Further studies are needed to uncover whether Sirt1/Claudin-1 is important in the early stages and whether Nampt/Sirt6/TIMP-1 is significant in the middle to late stages of human diabetic nephropathy, similar to that in murine models." (PMID 38587753, 2024). "Consistently, another prior study came indicated that Nampt depletion was associated with TIMP-1 activation, and could be further used to predict retarded ECM production of fibroblasts in diabetic nephropathy." (PMID 34967693, 2022). "Diabetic nephropathy (DN) patients had a significant reduction in serum levels of MMP2, TIMP1 and TIMP2 compared to the controls." (PMID 37445827, 2023). "Given these considerations, we hypothesised that high plasma levels of MMP-9 and its inhibitor TIMP-1 as well as NGAL can be related to chronic microvascular complications in individuals with type 1 diabetes, such as diabetes nephropathy and diabetes neuropathy." (PMID 33775157, 2021).
left ventricular hypertrophy (10 papers, 2011 to 2024). Enlargement of the LEFT VENTRICLE of the heart. "Higher serum levels of MMP-9 and tissue inhibitor of metalloproteinases-1 (TIMP-1) are involved in the pathogenesis of left ventricular hypertrophy by cleaving intracellular myosin filaments." (PMID 33102575, 2020). "Some authors have suggested that increases in MMP-7 MMP-9, and TIMP-1 levels are predictive of the presence of left ventricular hypertrophy." (PMID 33419373, 2020). "This is supported by studies in animal models showing elevation of plasma TIMP-1 in type 1 diabetic minipigs with left ventricular hypertrophy, increased cardiac fibrosis and cardiac dysfunction." (PMID 25848912, 2015). "Investigations have examined hypertensive patients with left ventricular hypertrophy, observing higher levels of TIMP-2, TIMP-1, and TIMP-4." (PMID 33419373, 2020).
leukemia (10 papers, 2010 to 2025). A malignant (clonal) hematologic disorder, involving hematopoietic stem cells and characterized by the presence of primitive or atypical myeloid or lymphoid cells in the bone marrow and the blood. "Some studies have reported elevated levels of TIMP-1 in plasma of leukemia patients, which is associated with the proliferation and migration abilities of leukemia cells." (PMID 35845981, 2022). "In this context, it has been reported that thymoquinone consumption moderated the levels of IL-6 and subsequently suppressed MMP-1, MMP-3, VEGF, and decreased TIMP-1 in Leukemia." (PMID 36518397, 2022). "Of note, previous investigations demonstrated that among 23 cytokines differentially expressed, at the molecular level, between normal and leukemic BM, only TIMP-1 was confirmed at the protein level suggesting a role in leukemia initiation and progression." (PMID 27903985, 2017). "In the present study we investigated, in vitro, the function and molecular pathways mediated by TIMP-1 in the microenvironment of AML, providing further evidence to support the relationship between inflammation and leukemia." (PMID 27903985, 2017). "TIMP-1 was reported to stimulate human osteosarcoma MG-63 cell, Raji lymphoma cell, and UT7 leukemia cell proliferation." (PMID 26556867, 2015). "TIMP-1 increases cell proliferation through the activation of p38 and JNK1/2 in UT7 leukemia cells and through the activation of the extracellular signal-regulated kinase (ERK) and p38 pathways in MDA-MB-435 cells." (PMID 26556867, 2015). "Recently, we suggested a potential role of MMP-9, MT1-MMP, TIMP-1, TIMP-2 and VEGF in the pathogenesis of canine leukaemia." (PMID 23641796, 2013).